ALK (ALK receptor tyrosine kinase)
Diseases named in the same sentence as ALK in open-access papers (continued):
Sharing a sentence is not in itself a finding about the gene and the disease.
lung adenocarcinoma (continued). "Additional relatively rare genetic alterations in lung adenocarcinoma, such as ALK, have also attracted attention in recent years." (PMID 34596344, 2021). "Oncogenes were detected in 64% of lung adenocarcinomas, while available information in relation to EGFR, BRAF, KRAS, ALK, ROS1, and MET gene mutations in lung adenocarcinomas are growing steadily." (PMID 34708154, 2021). "Several driving mechanisms other than EGFR, such as ALK‐related fusion oncogenes, have been uncovered in lung adenocarcinoma and can also regulate ERK and AKT signaling." (PMID 33152171, 2021). "We present a case of ALK-rearranged lung adenocarcinoma with acquired resistance to ALK inhibition, in which the BRAF V600E mutation is a novel resistance mechanism." (PMID 33663128, 2021). "Recently, several machine learning models based on CT images and clinical features have been developed to predict ALK rearrangement in lung adenocarcinoma." (PMID 33738250, 2021). "The most common primary site of ALK‐positive primary lung adenocarcinoma was the lower lobe, and the proportion in the positive and negative groups was 47.5% versus 33.3%." (PMID 34596344, 2021). "In 2011, crizotinib was first approved by the United States Food and Drug Administration to treat locally advanced or metastatic ALK-positive lung adenocarcinoma." (PMID 34530849, 2021). "Here, we report a case of brigatinib-induced TLS after treatment with sequential anaplastic lymphoma kinase (ALK) inhibitors in a patient with advanced ALK-rearranged lung adenocarcinoma." (PMID 34987411, 2021). "Female patients with lung adenocarcinoma harboring ALK that was rearranged and treated with ALK inhibitors such as crizotinib or ceritinib obtain similar benefits as men." (PMID 33466597, 2021). "We report a patient with ALK-positive lung adenocarcinoma who developed meningeal carcinomatosis after treatment with alectinib and brigatinib." (PMID 34596160, 2021). "ALK rearrangements occur in 3–5% of lung adenocarcinomas, consequent to an inversion on the short-arm of chromosome 2 joining its 3′ end with the 5′ end of the echinoderm microtubule-associated protein-like 4 (EML4), resulting in an EML4-ALK chimeric protein." (PMID 34915883, 2021). "ALK mutation was viewed as an independent favorable prognostic predictor for OS according to our study; ALK rearranged patients had a better prognosis than other lung adenocarcinoma cases." (PMID 34596344, 2021). "In this study, we fully analyzed the clinical features and prognosis of ALK‐positive lung adenocarcinoma patients, and the effect of ALK inhibitors on the prognosis of ALK‐positive postoperative lung adenocarcinoma patients based on clinical data." (PMID 34596344, 2021). "Post‐therapy specimens demonstrated PD‐L1 heterogeneity and an acyl glycerol kinase to B‐rapidly accelerated fibrosarcoma (AGK‐BRAF) fusion in a patient with an EML4‐ALK–positive lung adenocarcinoma as a potential resistance mechanism to ALK inhibitor therapy." (PMID 31747139, 2020). "All these 293 patients were lung adenocarcinoma patients with ALK-rearrangement and were treated with ALK-TKIs in all lines setting (postoperative adjuvant treatment, first line treatment, second line treatment and other conditions)." (PMID 32299384, 2020). "In the current cohort, there were 23.8% individuals still surviving to the last follow‐up, 57% cases with KPS ≥90, 42.8% patients at EGFR or ALK positive, and the vast majority of patients were lung adenocarcinoma." (PMID 33027555, 2020). "In conclusion, our findings highlight the feasibility of non-invasively predicting the ALK genetic status in lung adenocarcinomas using an integrated model that combines clinical, conventional CT, and radiomic features." (PMID 32266148, 2020). "Upregulation of NHERF1 in lung adenocarcinoma needs to be scrutinized during the administration of ALK-targeting drugs." (PMID 32164629, 2020).
lung adenocarcinoma (continued). "Several oncogenic drivers have been identified in lung adenocarcinoma, including mutations in the epidermal growth factor receptor (EGFR), fusions of anaplastic lymphoma kinase (ALK), and rearrangements of ROS proto-oncogene 1 receptor tyrosine kinase (ROS1)." (PMID 32677962, 2020). "In this report, we identified a rare double ALK fusion, EML4-ALK and CDK15-ALK, in the patient with lung adenocarcinoma." (PMID 33157918, 2020). "Clinical characteristics of ALK– and ALK+ lung adenocarcinoma patients in the primary and test cohort." (PMID 32266148, 2020). "In Sperduto’s research, significant prognostic factors included the classical four factors (age, KPS, extracranial metastases, and number of BM) and two molecular factors: EGFR and ALK mutant status, which frequently occurred in lung adenocarcinoma." (PMID 33194635, 2020). "Patients with stage IIIB-IV lung adenocarcinoma taking epidermal growth factor receptor (EGFR) TKIs or anaplastic lymphoma kinase (ALK) inhibitors were enrolled prospectively from June 2012 to February 2015." (PMID 33306683, 2020). "In contrast to the excellent activity of TKIs in mutant lung adenocarcinoma, TKIs showed a limited response in the PLELC patients with EGFR/ALK mutation in this study." (PMID 31794146, 2020). "KEY POINTS: SIGNIFICANT FINDINGS OF THIS STUDY: ECMO was important to maintain oxygenation during airway intervention for acute respiratory failure due to critical lung adenocarcinoma with ALK gene rearrangement." (PMID 32844533, 2020). "Together, we identified a rare double ALK fusion variant, EML4-ALK and CDK15-ALK, in a patient with lung adenocarcinoma." (PMID 33157918, 2020). "They identified a significantly higher proportion of ALK fusions in lung adenocarcinoma in Asians compared to Whites." (PMID 32460789, 2020). "In summary, we represented a rare double ALK fusion composed of a classic fusion variant of EML4-ALK and a newly discovered CDK15-ALK in a lung adenocarcinoma." (PMID 33157918, 2020). "On other hand, alteration on the Epidermal Growth Factor Receptor (EGFR) gene is found in 15% of lung adenocarcinoma and translocations of the Anaplastic Lymphoma Kinase (ALK) gene occur in 3%-7% of lung adenocarcinoma." (PMID 32111002, 2020). "EGFR TKIs, gefitinib, erlotinib, and afatinib, and ALK inhibitors, crizotinib and ceritinib, have prolonged progression-free survival (PFS) rates in advanced lung adenocarcinoma patients with sensitive EGFR mutations and ALK rearrangement, respectively." (PMID 33306683, 2020). "Thirteen lung adenocarcinoma patients suffered EGFR gene mutations, and fifteen lung adenocarcinoma patients had ALK gene mutations." (PMID 32296026, 2020). "Conventional CT features of ALK– and ALK+ lung adenocarcinoma patients in the primary and test cohort." (PMID 32266148, 2020). "Now, we are screening some lung adenocarcinoma cell lines harboring gene mutations, such as EGFR mutations, ALK rearrangement, KRAS mutations, and BRAF mutation, and other cell lines without gene mutations to detect MTAP gene and protein expression." (PMID 31965001, 2020). "An ALK-positive and crizotinib-sensitive lung adenocarcinoma cell line H3122 was used as the laboratory model for experiments." (PMID 32164629, 2020). "The dominant mutations found frequently in lung adenocarcinomas, such as EGFR, ALK and KRAS mutations, are uncommon in SQCC." (PMID 31829519, 2020). "ALK arrangement was positive in 6.7% (114/1700), 2.0% (8/396), and 5.6% (108/1913) in lung adenocarcinoma, SCC and NSCLC, respectively." (PMID 31794146, 2020). "Upon activation, ALK plays a primary role in the development of lung adenocarcinoma, as well as colorectal and breast cancers." (PMID 33255340, 2020). "Extracellular vesicles (EVs) produced by ALK-translocated lung adenocarcinoma cell lines, which were rendered resistant to the ALK-TKIs crizotinib or ceretinib, were found to contain elevated levels of miRNA-486 amongst other non-coding RNAs." (PMID 31979312, 2020).
lung adenocarcinoma (continued). "The importance of the ALK expression pattern for prognosis of lung adenocarcinoma patients was determined based on information in the PrognoScan microarray database, using a threshold COX p-value of 0.05." (PMID 33255340, 2020). "MiR-1343-3p expression pattern appeared to exhibit distinctive clinicopathological implications in ALK-rearranged lung adenocarcinoma." (PMID 32905397, 2020). "By characterization the effects of NHERF1 with its regulation on tumor cell responses to crizotinib, we have demonstrated a dynamic interplay between NHERF1 and ALK signaling in lung adenocarcinoma cells." (PMID 32164629, 2020). "The possible mechanisms of NHERF1 and its role in the cell sensitivity to crizotinib were investigated using an ALK-positive and crizotinib-sensitive lung adenocarcinoma cell line H3122." (PMID 32164629, 2020). "The fusion gene of EML4-ALK was discovered in lung adenocarcinoma in 2007; since then, fusion alterations of ALK, RET, and ROS1 genes have been found in about 4–7% of patients with lung adenocarcinoma." (PMID 31083279, 2019). "For instance, 17% of lung adenocarcinoma shows sensitive EGFR mutation, with 7% showing ALK mutation and 3% showing MET mutation." (PMID 31766180, 2019). "As the largest case series of ovarian metastasis from lung adenocarcinoma, our findings indicate that ALK rearrangement is the most common molecular alteration." (PMID 31455365, 2019). "For example, crizotinib has been demonstrated to be an effective targeted therapy in patients with lung adenocarcinoma harboring ALK or ROS1 fusions." (PMID 31083279, 2019). "A recent update to that research suggested that two additional factors, namely, EGFR and ALK alterations in patients with lung adenocarcinoma, can be used to better evaluate the prognosis of such patients." (PMID 31655564, 2019). "Histopathologically, this ALK rearrangement in lung adenocarcinoma appears to promote the unique features of solid and/or signet ring cells." (PMID 31455365, 2019). "A panel of drug resistant subclones of ALK-translocated lung adenocarcinoma cell lines, namely FA34 and FA121, was established." (PMID 30658414, 2019). "Anaplastic lymphoma kinase (ALK) gene rearrangements are detected in 3%-7% of patients with lung adenocarcinoma 1-2." (PMID 31777594, 2019). "Lung adenocarcinoma can be classified according to the presence of major driver mutations in EGFR, KRAS, ALK, and BRAF, which confer clinical benefits to the subset of patients harboring them." (PMID 31083279, 2019). "Pathological diagnosis of adenosquamous carcinoma is actually difficult; therefore, it is necessary to review the tumor composition when encountering cases of ALK-positive lung adenocarcinoma that respond poorly to ALK inhibitors." (PMID 31030664, 2019). "Although the ovary is an uncommon metastatic site in the female reproductive tract, uterine cervix metastasis from lung adenocarcinoma harboring ALK rearrangement has been reported, as have concurrent cervix and breast metastases." (PMID 31455365, 2019). "For instance, 50% of Asian patients and 10–15% of Caucasian patients with lung adenocarcinoma are EGFR mutation-positive, with 5% of NSCLC being ALK positive and 1% of NSCLC patients being ROS1 positive." (PMID 31766180, 2019). "In this review we will briefly discuss EGFR, ALK, and K-Ras gene alterations in lung adenocarcinoma." (PMID 31134065, 2019). "A 47-year-old female with ALK-rearranged lung adenocarcinoma developed leptomeningeal metastasis (LM) after progression on first-line crizotinib." (PMID 31766077, 2019). "Mutations in EGFR (epidermal growth factor receptor 1) and KRAS (Kirsten rat sarcoma viral oncogene homolog GTPase) and ALK (anaplastic lymphoma kinase) rearrangements are mostly found in lung adenocarcinoma, accounting for 30–40% of NSCLCs." (PMID 31795465, 2019). "We present the case of an old woman with ALK-rearranged stage IV lung adenocarcinoma who received crizotinib." (PMID 31250326, 2019).
lung adenocarcinoma (continued). "Approximately 3%–5% of lung adenocarcinoma is driven by anaplastic lymphoma kinase (ALK) fusion oncogene, whose activity can be suppressed by multiple ALK inhibitors." (PMID 31613427, 2019). "Mutations in 59 cancer-associated genes and fusions of ALK and ROS1 were analyzed to understand the molecular features of young patients with lung adenocarcinoma." (PMID 31387567, 2019). "In cases of ALK-positive lung adenocarcinoma poorly responsive to treatment, re-examination of the tissue should be considered because there is a possibility of adenosquamous carcinoma." (PMID 31030664, 2019). "A case of successful salvage surgery following multimodal therapy in advanced ALK‐rearranged lung adenocarcinoma is described." (PMID 31285825, 2019). "These circulating EV-RNA levels have been found to correlate with disease progression of EML4-ALK-translocated lung adenocarcinoma in patients prescribed ALK-TKI treatment." (PMID 30658414, 2019). "Meanwhile, first line Alk kinase inhibitor therapy with crizotinib is the current standard of care in ALK rearranged lung adenocarcinoma (LUAD) with increased progression-free survival compared with conventional chemotherapy." (PMID 29580750, 2018). "The profound initial responses observed with the use of targeted therapies, such as ALK inhibitors, in the treatment of oncogene-driven lung adenocarcinoma has demonstrated the value of identifying the dominant signaling pathways driving the cancer." (PMID 29507657, 2018). "His final diagnosis was stage IV ALK + adenocarcinoma of the lung with metastasis to pleura, mediastinum, and bones." (PMID 30336782, 2018). "EML4/ALK is the most common ALK fusion found in lung adenocarcinoma (4 to 7% of cases) while KIF5B/ALK is the second common in frequency (0.5%)." (PMID 30336782, 2018). "We used whole tumor sections from surgically resected lung adenocarcinoma patients documented to be ALK+ by chromogenic IHC and/or FISH." (PMID 30326973, 2018). "In summary, we report here the first MTP-based IF protocol for assessment of ALK protein expression in FFPE tumor tissue of lung adenocarcinoma patients." (PMID 30326973, 2018). "ALK-rearranged lung adenocarcinoma, comprising 4‒5% of lung adenocarcinomas, is clinicopathologically characterized by a TTF-1 cell lineage, an acinar structure with mucin/signet-ring cell morphology, non-/light-smoking history, and young onset." (PMID 29538329, 2018). "Here, we presented a case with ALK positive lung adenocarcinoma getting clinical benefit of 7 months of PFS from bevacizumab to pemetrexed treatment after two failed courses of ALK-inhibitor therapy; and the toxicity was well tolerated." (PMID 29318404, 2018). "In this context, particularly relevant were the studies carried out in lung adenocarcinomas with EGFR mutations and ALK rearrangements." (PMID 30060526, 2018). "FFPE tumor whole sections from 14 resected lung adenocarcinoma patients documented to be ALK positive (ALK+) by automated chromogenic IHC and/or FISH were used." (PMID 30326973, 2018). "We present a case of a patient with stage IV anaplastic lymphoma kinase (ALK) positive adenocarcinoma of the lung who underwent stereotactic radiosurgery to her brain metastases and received targeted treatment." (PMID 29541558, 2018). "We presented the first case of ALK-rearranged lung adenocarcinoma with major pathological response in resected specimens after treatment with alectinib." (PMID 29524063, 2018). "For example, adding bevacizumab to chemotherapy was found to effectively control radioresistant brain metastases in an ALK-rearrangement lung adenocarcinoma patient." (PMID 29318404, 2018). "In this study, we have used the novel technology of microfluidic-based immunofluorescence for the assessment of ALK status in lung adenocarcinoma patients, using FFPE tumor tissue whole sections from surgical specimens." (PMID 30326973, 2018).
lung adenocarcinoma (continued). "A 65-year-old female with a mental illness (bipolar disorder) was referred to our institute for the treatment of ALK-rearranged lung adenocarcinoma originating from the left lower lobe." (PMID 29524063, 2018). "Patients with advanced HER2-mutant lung adenocarcinomas showed an inferior outcome of first line pemetrexed-based chemotherapy compared to those with ALK/ROS1 rearrangements, which strengthen the need for effective HER2-targeted drugs in clinical practice." (PMID 29587667, 2018). "Mutations of the epidermal growth factor receptor (EGFR) gene and chromosomal rearrangement of the anaplastic lymphoma kinase (ALK) gene were among the first established molecular targets for therapy in lung adenocarcinoma." (PMID 29554880, 2018). "First, the final results of the Profile 1014 study provided evidence that crizotinib treatment elicited an improvement of overall survival compared to chemotherapy in patients with advanced ALK+ lung adenocarcinoma." (PMID 30060526, 2018). "We were able to detect specific ALK immunoreactivity on tumor epithelia of lung adenocarcinoma in a fast, reliable, and automated manner, confirming the IHC results obtained by routinely used staining procedures." (PMID 30326973, 2018). "Anaplastic lymphoma kinase (ALK) is a key oncogenic driver in lung adenocarcinoma patients and its fusion proteins are routinely assessed." (PMID 30326973, 2018). "Some of the classical gene fusion examples involving a kinase-coding gene are EML4-ALK in lung adenocarcinoma, ALK-RET in colorectal cancers, and VCL-ALK in renal cell carcinoma (RCC)." (PMID 29455652, 2018). "The most incident molecular alterations in lung adenocarcinoma, namely, KRAS mutations, EGFR mutations and ALK translocations, have been linked to MAPK activation." (PMID 29731995, 2018). "Here, we present the first surgical case of ALK-rearranged lung adenocarcinoma with major pathological response in resected specimens after treatment with alectinib." (PMID 29524063, 2018). "In one study, extensive amplification of the ALK fusion gene was detected in 18 patients with lung adenocarcinoma resistant to crizotinib and in acquired drug resistant cell lines with H3122 (including EML4-ALK mutant 1)." (PMID 29455664, 2018). "Anti-anaplastic lymphoma kinase (ALK)-targeted therapy dramatically improves therapeutic responses in patients with ALK-rearranged lung adenocarcinoma (Ad-LC)." (PMID 29844868, 2018). "EGFR mutations occur in up to 50% of all East Asian lung adenocarcinoma patients, while a genetic rearrangement resulting in the fusion of the 5′ region of EML4 to the 3′ region of ALK occurs in 2%–5% of NSCLC patients." (PMID 29764505, 2018). "Here, we presented a case with ALK positive lung adenocarcinoma getting significant clinical benefit from bevacizumab to pemetrexed combination therapy who had failed two courses of ALK-inhibitor therapy." (PMID 29318404, 2018). "All of these implied that pemetrexed should be preferentially considered for the treatment of ALK-rearrangement lung adenocarcinoma." (PMID 29318404, 2018). "The newly developed protocol for immunofluorescent detection of ALK protein with the MTP device confirms chromogenic IHC results on FFPE lung adenocarcinoma specimens." (PMID 30326973, 2018). "A total of 106 ALK positive lung adenocarcinoma cases were collected for assessment of intratumour heterogeneity of ALK gene translocation, which were stained by the fully automated Ventana ALK D5F3 immunohistochemistry (IHC) analysis." (PMID 28887531, 2017). "In lung adenocarcinoma, fusions of ALK, RET, and ROS1 have been shown to be targetable genetic alterations." (PMID 28894699, 2017). "In summary, the prevalence of ALK rearrangement detected by Ventana IHC testing in Chinese patients with early-stage lung adenocarcinoma was 7.9%." (PMID 29156778, 2017).